GZMB (granzyme B)
Diseases named in the same sentence as GZMB in open-access papers (continued):
Sharing a sentence is not in itself a finding about the gene and the disease.
tumor (continued). "To investigate possible mechanisms involved in the ability of RU486 to enhance efficacy of Ad5IL-12, we compared granzyme B levels produced from isolated popliteal lymph node cells (the TSLN) co-cultured for 24 hrs with irradiated TRAMP-C1 tumor cells as targets." (PMID 20946663, 2010). "In addition, we found that combination therapy increased the capacity of TSLN lymphocytes to produce Granzyme B in response to tumor cell targets." (PMID 20946663, 2010). "Additionally, CD8+ T cells isolated from spleens of mice treated with our combination therapy showed enhanced Granzyme B production following stimulation with irradiated 4T1 cells ex vivo, thus demonstrating an improved anti-tumor CTL memory effect." (PMID 19956757, 2009). "Thus, in mouse, both granzyme B and perforin are relevant for Treg cell-mediated suppression of tumor clearance in vivo." (PMID 20169125, 2009). "Bcl-2 expressed by tumour cells could sequester activated Bid, and therefore block apoptosis in the face of immune cell-derived granzyme-B." (PMID 17311012, 2007). "As NK cells experience a reduction in the amount of Perforin and Granzyme B after serially killing of tumor cells but survive the process, we wanted to investigate whether the cytolytic ability of these NK cells can be restored." (PMID 17389917, 2007). "The over-expression of serpins by some tumor cells could also inhibit granzim A or granzyme B lytic activity too." (PMID 15784149, 2005). "Mechanistically, ILC1s characterized by high GZMA/GZMB expression represent the primary subset accumulating within tumors and are responsible for enhancing antitumor immunity, which can induce Gasdermin D cleavage in tumor cells to initiate tumor pyroptosis for a cascade of cancer-immunity cycle." (PMID 41998137, 2026). "Furthermore, Remodelin combined with anti–PD-1 treatment substantially increased the infiltration of CD8+ T cells into the tumor, accompanied by a high percentage of GzmB+ and IFN-γ+ CD8+ T cells, demonstrating that NAT10 inhibition enhances the effects of PD-1 blockade." (PMID 41542770, 2026). "To evaluate whether curcumin enhances T cell activation and cytotoxic capacity while improving the tumor microenvironment, we performed PD-L1/PD-1 blockade assay and analyzed factors associated with T cell activation and cytotoxicity (FOXP3, GZMB, c-caspase-3 and IFN-γ)." (PMID 41522360, 2026). "While generally cytotoxic, Tc1 cells produce cytokines such as interferon-γ (IFN-γ), tumor necrosis factor-α (TNF-α), and granzyme B, which may exert immunomodulatory effects and, under certain conditions, support tumor progression through mechanisms that resemble those of CD4+ helper T cells." (PMID 40723153, 2025). "Analysis of effector activity of these tumor-infiltrating CD4+ T cells revealed that T-bet-deficient CD4+ T cells had markedly impaired functionality in both saline and M002 treatment groups, as the IFNγ+TNFα+ population and the expression of GzmB were significantly reduced." (PMID 39885128, 2025). "Moreover, a pan-cancer study identified a tumor-enriched NK cell subset—tumor-associated NK (TaNK) cells—which display elevated stress-response genes (e.g., DNAJB1/HSP40) and reduced levels of cytotoxic molecules (e.g., granzyme B, perforin)." (PMID 40297580, 2025). "Similarly, exosomes derived from CD8+ T cells carry key cytotoxic molecules, including granzyme B and miR-298–5p, which target and deplete mesenchymal tumor stromal cells, such as CAFs and mesenchymal stem cells (MSCs), thereby reducing tumor invasiveness and metastasis." (PMID 40693234, 2025). "Moreover, DFFB deletion in tumor cells may attenuate killing by granzymes, as inactive DFFB is cleaved and activated by granzymes B and M. BAD/BAX deletions in tumor cells may also blunt rapid killing by granzyme B, which activates BAX and caspase-3." (PMID 41175874, 2025).
tumor (continued). "Additionally, both EDAR knockdown and NFκB inhibitor pretreatment weakened T cell cytotoxicity against NPC cells, reduced the number of T cells recruited by tumor cell supernatants, and decreased the proportion of GZMB+CD8+ T cells in the supernatant‐treated T cell population." (PMID 40995667, 2025). "Interestingly, this cluster also has an elevated expression of MYH3, an embryonic form of myosin heavy chain, several cardiac cytoskeletal genes (ACTC1, TNNT2), and SERPINB9, which has previously been shown to protect tumor cells from granzyme B secreted by cytotoxic T lymphocytes." (PMID 41373578, 2025). "Also, immunohistochemical and flow cytometric analyses demonstrated significantly elevated Granzyme B expression in tumor tissues, coupled with enhanced IFN-γ production capacity in CD8 + T cells, indicative of augmented cytotoxic potential in tumor-infiltrating immune cells." (PMID 40993737, 2025). "Preclinical data from murine models have demonstrated that lenvatinib induces tumour immune microenvironment modifications (e.g., reduction of tumour-associated macrophages (TAMs) and increase of activated CD8+ T cells secreting interferon (IFN)-γ+ and granzyme B)." (PMID 41502513, 2025). "Notably, there was a substantial increase in the number of perivascular CD8+ T cells and CD8+ granzyme B+ cells, which may have contributed to the enhanced anti-tumor efficacy observed with the combined treatment." (PMID 39744218, 2025). "However, the specific role of CD4+ granzyme B+ T cells in tumor immunity remains unclear and warrants further investigation." (PMID 39744218, 2025). "Two GZMB+ clusters (GZMB+ early-activation and GZMB+ late-activation/effector memory-like) displayed high expression of cytotoxicity markers, high TCR clonality and strong tumor association, evidenced by the significant overlaps of their TCRs with those identified in patient-matched tumor biopsies." (PMID 40610460, 2025). "Additionally, granzyme B+ cells were more abundant in tumors treated with EcN-IL-15/CR + L than in EcN-IL-15/CR or EcN/CR + L groups, indicating enhanced lymphocyte cytotoxicity for tumor elimination." (PMID 40532661, 2025). "Moreover, immunohistochemical staining revealed elevated expression of CD8, GZMB, and CD11c in tumor tissues upon INHBA knockdown, indicating that silencing INHBA may enhance CD8+ T cells and dendritic cells (DCs) infiltration within the TME." (PMID 41449244, 2025). "Additionally, through autophagic processes, tumor cells become capable of degrading granzyme B, a factor secreted by activated CTLs and NK cells with the aim to induce apoptosis in target cells, thereby effectively blocking immune cell induced tumor cell destruction." (PMID 38611008, 2024). "During the process of T cells killing target cells, the granzyme B expressed in T cells is released into target cells through direct intercellular contact (immune synapse), and then the granzyme B within target cells activates the apoptosis-related pathway of tumor cells." (PMID 38672132, 2024). "Detection of the tumour GZMB marker by flow cytometry and immunohistochemistry methods, respectively, showed a significant upregulation of GZMB expression in the MCT4i group, indicating that inhibiting SLC16A3 could effectively enhance the cytotoxic ability of immune cells." (PMID 39656344, 2024). "Notably, HLA-G is increased in MIBC with an immune evasive microenvironment (high PD-L1 tumor cell expression, NK cell depletion, granzyme B (GZMB)/CD8 ratio reduction, MHC class I (MHCI) expression reduction) that are characterized by immunosuppressive features and poor prognosis." (PMID 39469714, 2024). "Interestingly, Jia and colleagues proposed in their functional experiment studies in AML patients that TIGIT expression might be correlated with increased secretion of IFN-γ and TNF-α cytokines and granzyme B, supporting the NK anti-tumor activity in AML." (PMID 39339180, 2024).
tumor (continued). "Considering that a significant proportion of the CD8+ TILs exhibit positivity for granzyme B, and their density also exhibited an increase in splenectomized mice, it is reasonable to designate them as the principal activated effector cells responsible for tumor reduction." (PMID 38402307, 2024). "Finally, the bacterium Akkermansia_muciniphila may play a role in GZMB regulation, potentially influencing the tumor immune microenvironment." (PMID 39376571, 2024). "The frequency of VISTA-positive immune cells within human clear cell renal cell carcinoma tumors is negatively associated with the frequency of tumor-infiltrating CD8+ T cells and granzyme B/perforin-positive or TNF-α-positive T cells, suggesting that intratumoral VISTA may suppress T-cell function." (PMID 39482534, 2024). "In addition, Rg3 could decrease the tumor volume and enhance anti-tumor T cell immunity as evidence by the upregulated expression of Granzyme B and perforin in CD8+T cells, along with elevated serum IL-2, IFN-g and TNF-a level in Rg3-treated mice." (PMID 39247194, 2024). "Therefore, we hypothesised that PD-L1 expression, according to the PBRM1 expression status, could affect perforin and granzyme B mRNA levels by inhibiting the tumour-killing activity of immune cells." (PMID 39375538, 2024). "It is possible that the presence of granzyme B in ta-ILC2s is not only a consequence of plasticity induction, but also a potential mechanism that facilitates the acquisition and presentation of antigen from dying tumour cells, supporting Th1-related responses via this potential novel pathway." (PMID 38172434, 2024). "MI was induced in CCR2-diphtheria toxin receptor mice, which had depleted monocytes and showed decreased effects on tumor growth, decreased tumor Ly6Chi monocytes, and a decrease in the proportion of regulatory T cells, as well as an increased proportion of activated T cells (granzyme B+)." (PMID 38279150, 2024). "However, increasing glucose concentrations from 5.8 mmol/l to 25 mmol/l caused neither an increase in the granzyme B response nor an increase in the expression of the apoptosis marker CC3 in tumor cells." (PMID 38515569, 2024). "The higher abundance of GZMB positive cells in the PRSlow group may account for its capacity to effectively screen and identify patients exhibiting pyroptosis and activation of anti-tumor immune response." (PMID 38773976, 2024). "Notably, granzyme B (GZMB) displayed a threefold change in expression in 76% of the tumor samples." (PMID 38979413, 2024). "Notably, preclinical research showed that the antitumor activity of lenvatinib will improve when combined with ICIs by reducing tumor-associated macrophages (TAMs) and increasing the percentage of activated CD8+ T cells secreting interferon (IFN)-γ+ and granzyme B (GzmB)." (PMID 37664019, 2023). "Simultaneous blockade of TIGIT and PD-L1 has elicited tumor rejection and antigen-specific protection in CT-26 tumor-bearing mice, and TIM-3 has been implicated in inhibiting the cytotoxic function of Vδ2 T cells by suppressing the release of granzyme B and perforin." (PMID 38077396, 2023). "In addition, among the tumor-infiltrating lymphocytes (TILs), TREM1 deficiency led to significant attenuation in exhausted CD8+ T (T Exh) cells (CD8+Tim-3+CTLA-4+) while increasing the proportion of cytotoxic CD8+ T (T Cyt) cells (CD8+GzmB+CD25+)." (PMID 37651197, 2023). "Interestingly, in the OKT3-T cell treated group, while a small amount of CD8+ T cells infiltrated the tumor area, these T cells did not actively release granzyme B. In contrast, the anti-PSMA BsAb-armed-T cells released a large amount of granzyme B in the tumor area." (PMID 37259079, 2023).
tumor (continued). "To test whether the alisertib-induced PD-L1 expression in tumor cells affected the function of cytotoxic T cells in the mouse tumor microenvironment, we performed immunohistochemical staining of cytotoxic T cells with granzyme B in tumor tissues isolated from BALB/c mice." (PMID 36928177, 2023). "Therefore, we assessed the accumulation of CD8+, CD4+ T cells, and NK cells and the concentrations of their effector molecules (IFN-γ and granzyme B) in the bronchioalveolar lavage fluid (BALF) of previously immunized mice that were subsequently challenged with 4T1 tumor cells." (PMID 36839766, 2023). "Furthermore, the amount of α-smooth muscle actin (α-SMA)+ fibroblasts at the tumor invasive front positively correlated with the number of macrophages (MØs), but negatively correlated with that of tumor-infiltrating granzyme B+ immune cells, and CD4+ and CD8+ T cells." (PMID 37254126, 2023). "However, only in the context of FAK deletion did we observe inhibition of tumour growth and elevated granzyme-B expression indicative of CD8 T-cell engagement, implying that co-depletion of FAK and STAT3 is complementary through enhancing both CD8 T-cell infiltration and PDAC cell immunogenicity." (PMID 36977556, 2023). "Furthermore, culturing of OVA-specific CD8+ T-cells on this SIN elevates the cellular levels of granzyme B expressed by these cells and increases their efficiency in killing ovalbumin-expressing cultured cancer cells, as well as their tumor suppressive activity, in vivo." (PMID 36937426, 2023). "Granzyme B is also a molecule that correlates with the anti-tumor activity of cytotoxic T cells, as PET (Positron Emission Tomography) measurements have shown that it may be used as an early biomarker of therapeutic response in cancer immunotherapy such as anti-PD-1 therapy." (PMID 37298408, 2023). "However, CASP10 was highly upregulated in the A1M group (based on data from only one tumor), indicating that A1M may activate the perforin/granzyme B pathway." (PMID 37076494, 2023). "Immunohistochemistry (IHC) analyses of the tumor samples obtained on day 6 after the beginning of the therapy were performed to evaluate the levels of tumor vascularization, proliferation, hypoxia, apoptosis, immune infiltration (granzyme B-positive cells), and necrosis." (PMID 36769077, 2023). "One of the most significantly upregulated proteins in the tumor periphery was granzyme B. In order to validate the differential expression of granzyme B in the tumor periphery in comparison to the tumor center, we stained all samples for granzyme B using conventional immunohistochemistry." (PMID 37894418, 2023). "High levels of expression of GZMB and FASL (encoding Granzyme B and Fas ligand) but low levels of IFNG and TNF (encoding Interferon-γ and TNF-α) in these exhausted-like T cells are suggestive of an altered cytotoxic profile but remaining capacity for tumor cell killing." (PMID 36609566, 2023). "The possible mechanisms may include the expression of HN protein in NDV-infected tumor cells, enhanced adhesion with NK cells, the release of more NK cell response cytokines (e.g., IFN-γ, TNF-α, perforin, and granzyme B), and the activation of apoptosis in tumor cells." (PMID 37107646, 2023). "In contrast, Th1‐like CD4+ T cells, characterized by the expression of CCL4, GZMA and GZMB were found to be involved in viral protein interactions, natural killer cell‐mediated cytotoxicity and the T cell receptor signaling pathway, revealing their positive roles in tumor immune defense." (PMID 36725337, 2023). "In addition, they still express various effector molecules, such as IFN-γ and granzyme B. These observations suggest that Tex cells at early stage may still be functional, but also imply that they are true tumor-reactive T cells within tumor microenvironment." (PMID 37881432, 2023).
tumor (continued). "In support of this hypothesis, IHC staining of paraffin tumor sections showed reduction of PD-L1+ cells, but increased infiltration of CD8+ T cells and granzyme B secretion in Atad3a-deficient tumors, with no changes in the number of Ki67+ tumor cells." (PMID 36627348, 2023). "Moreover, they express effector molecules, which are destined to kill tumor cells, including perforin 1, granzyme B and TNFα, as well as multiple pro-inflammatory cytokines that are characteristic for activated macrophages and Th1 cells, including IL-1β, IL-6, IL-2 and IFNγ." (PMID 37174085, 2023). "Notably, tumor and cytotoxic immune cell co-culture assays confirmed that overexpression of circCRIM1 increased the proportion of tumor cell death and promoted the expression of Granzyme B, IFN-γ, and TNF-α of CD8+ T and natural killer (NK) cells." (PMID 36672208, 2023). "Therefore, the expression of GZMB in combination with PD-L1 may be an essential biomarker of the tumor immune system." (PMID 37760424, 2023). "Therefore, Granzyme B PET may facilitate the direct visualization of those immune cells killing tumor cells, suggesting its predictive potential for a response to immunotherapy." (PMID 38067379, 2023). "First, activation of the receptor induces perforin expression and release of granzyme B, thereby mediating pore formation at the tumor cell membrane and leading to the entry of granzyme protease into the cell, which subsequently initiates apoptosis of tumor cells." (PMID 37508545, 2023). "Of note, it was interesting to observe the divergence in the potential killing mechanisms by germinal center B cells (TNFSF ligands) and plasma cells (granzyme B), suggesting that these two cell types could mediate very specific cytotoxic functions within the tumor microenvironment." (PMID 35392082, 2022). "Two small-molecule Bcl-2 inhibitors, HA14-1 and ABT-737, were found to improve the in vitro cytotoxicity of CTLs and NK cells to the lymphoma and melanoma cells, which might be attributed to sensitizing tumor cells to perforin and granzyme-B with drug treatments." (PMID 36080223, 2022). "However, FoxP3+ cells were increased while Granzyme B+ cells were decreased, which may also reduce cancer immune surveillance and lead to increased tumor multiplicity." (PMID 36185806, 2022). "The combinational effect of AHCC® and DICB therapy on tumor could be mediated by enhanced cytotoxicity and proliferation capacity of tumor infiltrating T cells as noticed by increased expression of granzyme B and Ki-67 in these cells in mice treated with AHCC® and DICB therapy." (PMID 35514996, 2022). "However, PI is different; it down-regulates the expression level of PD-1 on effector T cells in tumor tissues (even though it up-regulates PD-1 level of T cells in peripheral blood), and these T cells express and secrete perforin and granzyme B, instead of IFN-γ." (PMID 36429033, 2022). "A number of other immune-stimulatory genes were also upregulated, including the gene encoding granzyme B (GzmB; Log2FC 2.74, FDR = 3.49e−09) and Klrk1 (Log2FC 1.15, FDR = 0.016), which encodes NKG2D, the major NK- and T-cell receptor for recognition and elimination of tumor cells." (PMID 35131874, 2022). "Perforin and granzyme B may have a shared role in tumor killing but also β cell death in T1D." (PMID 35925682, 2022). "Furthermore, in a xenograft mouse model, 60 mg/kg of QUE inhibited tumor growth, the population of cytotoxic T cells increased and the expression of cytokines such as interferon-gamma (IFN-γ) and granzyme B in the tumor microenvironment increased to kill the tumor." (PMID 36551742, 2022). "Granzyme B (GzmB) and Granzyme A (GzmA) are apoptotic proteinase-like serine proteases that can activate caspase-3 and caspase-8 and be transferred to target cells by cytotoxic lymphocytes to trigger cell apoptosis, pyroptosis, and kill virus-infected cells and tumor cells." (PMID 36605130, 2022).